PLG (plasminogen)
Description:
[Plasmin]: Protease which primary function is to degrade fibrin, the main component of blood clots. Also cleaves other components of blood clots like thrombospondin-1/THBS1 and von Willebrand factor/VWF. Can also directly and/or through the activation of other proteases degrade the various components of the extracellular matrix including collagen, fibronectin and laminin. Thereby, regulates a variety of biological processes including embryonic development, tissue remodeling, and inflammation. In ovulation, weakens the walls of the Graafian follicle (By similarity). In vitro, it is also able to cleave several complement zymogens, such as C1, C4 and C5. [Angiostatin]: Has an antiangiogenic activity and inhibits neovascularization. Could act through the inhibition of the ATP synthase subunit ATP5F1A. (Microbial infection) Binds to OspC on the surface of B.burgdorferi cells, possibly conferring an extracellular protease activity on the bacteria that allows it to traverse host tissue. (Microbial infection) Interacts with dengue virus type 2 particles. Enhances dengue virus type 2 infection in Aedes aegypti mosquito midgut by increasing midgut internalization, resulting in higher infection rates and viral dissemination in mosquitoes.
Synonyms: HAE4
Tractability: Small molecule: an approved drug acts on it; a structure with a bound ligand is known; a high-quality ligand is known; it has a binding pocket of medium quality; it belongs to a druggable protein family. Antibody: UniProt places it where antibodies can reach, with high confidence; its Gene Ontology location is reachable by antibodies, with high confidence; UniProt predicts a signal peptide or a membrane-spanning region. PROTAC: its protein half-life has been measured; a small molecule that binds it is known. Other modalities: an approved drug acts on it.
Target class: Serine protease; Enzyme; Serine protease PA clan; Serine protease S1A subfamily; Protease
Gene: Protein-coding gene on chromosome 6 (160,702,105 to 160,754,097, forward strand). Ensembl gene ENSG00000122194.
Subcellular location: Secreted (Plasmin); Secreted (Angiostatin)
Subcellular location (Human Protein Atlas): Vesicles; Predicted to be secreted
Pathways (Reactome):
Extracellular matrix organization: Activation of Matrix Metalloproteinases; Degradation of the extracellular matrix
Hemostasis: Dissolution of Fibrin Clot; Platelet degranulation
Metabolism of proteins: Regulation of Insulin-like Growth Factor (IGF) transport and uptake by Insulin-like Growth Factor Binding Proteins (IGFBPs)
Signal Transduction: Signaling by PDGF
Gene Ontology:
Molecular function: apolipoprotein binding; endopeptidase activity; enzyme binding; kinase binding; protease binding; protein antigen binding; protein binding; protein domain specific binding; protein-folding chaperone binding; serine-type endopeptidase activity; signaling receptor binding; serine-type peptidase activity
Biological process: biological process involved in interaction with symbiont; blood coagulation; collagen catabolic process; extracellular matrix disassembly; fibrinolysis; negative regulation of cell-substrate adhesion; negative regulation of fibrinolysis; positive regulation of blood vessel endothelial cell migration; positive regulation of fibrinolysis; proteolysis; negative regulation of cell-cell adhesion mediated by cadherin
Cellular component: blood microparticle; cell surface; external side of plasma membrane; extracellular exosome; extracellular matrix; extracellular region; plasma membrane; platelet alpha granule lumen
Genetic constraint (gnomAD): Loss-of-function variants: 32 observed, 76.84 expected, observed/expected ratio (o/e) 0.42, 90% interval 0.31 to 0.56. The upper end of that interval is the gene's LOEUF score, 0.56, which puts it in group 2 of 6, group 1 being the genes least tolerant of losing a copy. Missense variants: 695 observed, 812.73 expected, observed/expected ratio (o/e) 0.86, 90% interval 0.8 to 0.91. Synonymous variants: 272 observed, 294.36 expected, observed/expected ratio (o/e) 0.92, 90% interval 0.84 to 1.02.
Gene-disease validity (ClinGen):
ClinGen rates the evidence that PLG causes each of these diseases.
hypoplasminogenemia (autosomal recessive): Definitive. A rare multi-system disease characterized by markedly impaired extracellular fibrinolysis leading to the formation of ligneous (fibrin-rich) pseudomembranes on mucosae.
Homologues: Orthologues: chimpanzee PLG (97% identical), macaque PLG (93% identical), dog PLG (83% identical), pig PLG (80% identical), mouse Plg (80% identical), rat Plg (78% identical), guinea pig PLG (78% identical), rabbit PLG (78% identical), tropical clawed frog plg (58% identical), zebrafish plg (57% identical), tropical clawed frog prss57 (15% identical). Paralogues in human: PLAT (22% identical), PRSS33 (13% identical), OVCH1 (12% identical), PRSS27 (12% identical), PLGLB1 (11% identical), PLGLB2 (11% identical), PRSS48 (11% identical), TMPRSS12 (11% identical), KLK15 (11% identical), KLK9 (10% identical), PRSS50 (10% identical), PRSS57 (10% identical), and 2 more.
Diseases named in the same sentence as PLG in open-access papers:
PLG is named in the same sentence as 339 diseases in open-access papers, as found by Europe PMC text mining. Sharing a sentence is not in itself a finding about the gene and the disease. The quoted sentences say what the papers report.
COVID-19 (45 papers, 2020 to 2025). A disease caused by infection with severe acute respiratory syndrome coronavirus 2. "Specifically, elevated levels of plasminogen and tPA have been shown to be associated with worse outcomes in COVID-19 patients, while TAFI has been shown to be a predictor of mortality in patients with sepsis." (PMID 37629265, 2023). "In this study, we did report a strong association between low levels of plasminogen and high rate of mortality in patients with COVID-19." (PMID 34354045, 2021). "In this study, we aimed to investigate the association between plasminogen levels and COVID-19-related outcomes in a population of 55 infected Caucasian patients (mean age: 69.8 ± 14.3, 41.8% female)." (PMID 34354045, 2021). "In particular D-dimer, aPTT, plasminogen, fibrinogen, and low platelet count have previously been suggested as parameters for risk and therapy stratification in patients with COVID-19." (PMID 33564744, 2021). "Low blood levels of plasmin and its precursor plasminogen correlate with a high risk for mortality and are associated with IL-6 upregulation in COVID-19 patients, reflecting its potential contribution to profibrogenic uPA accumulation and low-level fibrinolysis." (PMID 36674896, 2023). "However, the benefit or risk of plasminogen or plasmin (and the fibrinolytic system) to COVID-19 patients remain uncertain because of conflicting studies and merit further investigation." (PMID 37037462, 2023). "Therefore, in the present study, we aimed to analyze the association between plasminogen levels and the main COVID-19-related outcomes, including biological parameters, in a population of infected Caucasian patients." (PMID 34354045, 2021). "Given enhanced plasminogen as potential susceptibility factor for COVID-19, we detected increased levels inn = 8/17 versusn = 8/41 and decreased levels inn = 3/17 versus 7/41 in COVID-19 versus non-COVID-19." (PMID 33564744, 2021). "Importantly, a higher H-IPF level was associated with lower plasminogen levels in those COVID-19 patients who died." (PMID 34940584, 2021). "In addition, low levels of plasminogen were associated with 12-fold higher risk for mortality even after multiple adjustments, suggesting its power as independent predictor of worse outcomes in subjects with COVID-19." (PMID 34354045, 2021). "On the other hand, a significant decrease in functional plasminogen levels was found in the COVID-19+ group as compared to the other investigated groups." (PMID 40303405, 2025). "The results of this analysis showed that plasminogen, TAFI, and tPA were associated with mortality, which is consistent with previous studies that have shown an association between these biomarkers and COVID-19 severity and mortality." (PMID 37629265, 2023). "For example, inhalation of plasminogen has been shown to improve oxygen levels in a small group of patients with moderate COVID-19 and that low levels of plasminogen was reported to be correlated with mortality in COVID-19 patients." (PMID 37037462, 2023). "Further investigation is needed to determine the therapeutic potential of plasminogen in the treatment of post-COVID-19 pulmonary fibrosis." (PMID 36674896, 2023). "Abnormal amounts of fibrinolytic markers have been associated with poor outcome in COVID-19, including PAI-1, tPA, TAFI and plasminogen." (PMID 36294850, 2022). "Plasminogen at the dose of 10 mg was administered twice daily for severe/critical COVID-19 subjects (n = 8), and once daily for moderate COVID-19 subjects (n = 5)." (PMID 35908022, 2022). "To the best of our knowledge, we are the first demonstrating the direct impact of plasminogen levels with COVID-19 outcomes and prognostic parameters." (PMID 34354045, 2021). "COVID-19 patients with low levels of plasminogen showed a 12-fold significant increase in mortality compared to COVID-19 patients with normal or high levels of plasminogen (OR 12.57, 95% CI 2.46–64.0, β = 2.53, p = 0.002)." (PMID 34354045, 2021).
COVID-19 (continued). "Antiplasmin and plasminogen levels were similar in the supernatant of the controls, COVID-19 and Long COVID/PASC." (PMID 34425843, 2021). "In agreement with our results, a previous study demonstrated as high PAI-1 tracked most closely with impaired oxygenation efficiency in COVID-19 patients, and tPA was the best predictor of death, as activator of plasminogen, then leading to its consume." (PMID 34354045, 2021). "In further support of this, several groups have suggested modulation of the fibrinolytic pathway by targeting plasmin/plasminogen based on imbalances in protease levels in COVID-19 patients." (PMID 33869309, 2021). "On the other hand, cirrhotic patients exhibited significantly lower antiplasmin activity and plasminogen activity than COVID-19 patients, while ACE activity and plasma aldosterone concentration were higher." (PMID 34945736, 2021). "Relative to control and COVID-19 samples, plasminogen levels were slightly increased in the pellet deposits from Long COVID/PASC." (PMID 34425843, 2021). "The inhalation of plasminogen has improved the lung lesions in five clinically moderate COVID-19 patients and oxygen saturation in six clinically severe COVID-19 patients." (PMID 34371768, 2021). "As indicated by the impact on different components of the blood and coagulation system, such as plasminogen or fibrin in the case of COVID-19 and heme, respectively, both conditions can influence hemostasis." (PMID 33925394, 2021). "There is evidence that COVID-19 patients develop resistance to exogenous fibrinolytics, which may be due not only to the suppression of factors involved in plasminogen activation, but also to increased activity of fibrinolysis inhibitors." (PMID 39457048, 2024). "Overall, these findings highlight the importance of monitoring coagulation biomarkers in COVID-19 patients, particularly plasminogen, TAFI, and tPA, which may serve as predictors of disease severity and mortality." (PMID 37629265, 2023). "It was observed in COVID-19 patients that plasminogen activator inhibitor-1 (PAI-1), vitronectin, plasminogen, and tPA were elevated and fibrin clots formed from COVID-19 patient plasma showed altered fibrin network structures with elevated cross-linking and shorter fibrin fibres." (PMID 36998202, 2023). "A reduction in respiratory failure in COVID-19 patients with plasminogen treatment may suggest large deficits in endogenous plasminogen levels in these patients." (PMID 36551272, 2022). "We did not assess several key factors associated with hemostatic balance (e.g., antithrombin, plasminogen activators and plasminogen inhibitors), thus, our data should not be used to infer definitive safety of COVID-19 convalescent plasma." (PMID 35022488, 2022). "The inhalation of freeze-dried plasminogen was investigated in 13 patients with COVID-19 ARDS." (PMID 35908022, 2022). "The authors concluded that plasminogen treatment may be used at a larger scale, particularly to COVID-19 patients with clinical conditions quickly changing from moderate to severe conditions." (PMID 35908022, 2022). "A previous study, in line with our data, demonstrated that lower levels of plasminogen resulted in highest rate of admission to ICU in COVID-19 patients but without reporting the association with other biomarkers of the disease." (PMID 34354045, 2021). "Taken together these results suggest that in the complex pathway of COVID-19, levels of plasminogen may be indicated as independent predictor of mortality in these patients." (PMID 34354045, 2021). "Recently, plasminogen was suggested to play a pivotal role in controlling the complex mechanisms beyond COVID-19 complications, so it could be a useful prognostic marker and a potential therapeutic target." (PMID 34940584, 2021). "Moreover, low levels of plasminogen strongly correlated with mortality in COVID-19 patients even after multiple adjustments for presence of confounding." (PMID 34354045, 2021).
COVID-19 (continued). "An investigation into the efficacy of complement inhibitors (such as Eculizumab or Compstatin), and plasminogen activators specifically for T-PA, combined with Vitamin-D supplementation to alleviate symptoms in patients with severe/acute COVID-19, warrant exploration." (PMID 34786557, 2020). "Furthermore, randomized, controlled trials of plasminogen inhalation targeting COVID-19 are also ongoing." (PMID 32959003, 2020). "Moreover, the increased mortality in COVID-19 is associated with conditions, which are associated with endothelial dysfunction, low ACE2 expression, and high circulating plasminogen levels." (PMID 33391014, 2020). "Thus, in our analysis, we found that pre-COVID-19 dengue patients exhibited significantly higher levels of antithrombin and plasminogen than post-COVID-19 dengue patients, suggesting a potentially more anticoagulant and profibrinolytic profile in the earlier cohort." (PMID 41305453, 2025). "Thus, it has been proposed that nebuliser plasminogen activators, including pre-existing drugs, such as Tenecteplase, a modified recombinant tPA molecule, may be used as a treatment for COVID-19 patients, by facilitating fibrin degradation." (PMID 37175942, 2023). "Furthermore, plasminogen- activator-inhibitor type 1 (PAI-1), a strong inhibitor of fibrinolysis, was upregulated, while plasminogen and tissue plasmin-activator (tPA) concentrations were unaffected, implying that fibrinolysis was impeded in both groups of COVID-19 patients." (PMID 36851312, 2023). "In COVID-19, excess suPAR may bind to uPA, thus preventing uPA from activating plasminogen." (PMID 36142634, 2022). "Plasminogen may be another interesting therapeutic agent in the fight against COVID-19." (PMID 36286308, 2022). "Interestingly, plasminogen therapy was also tried in 13 patients with COVID-19." (PMID 34522166, 2021). "COVID-19 has been hypothesized to be a prothrombotic state due to endothelial dysfunction and increased hypoxia-inducible transcription factor in patients with severe pneumonia, and plasminogen activation inhibition in patients who develop sepsis." (PMID 33206661, 2020). "Admission IL-1β, and IL-33 were significantly lower, while IL-18 was significantly higher in cases when COVID-19 became more severe, along with significantly decreased FVIII, FXIII and plasminogen." (PMID 40303405, 2025). "COVID-19+ women exhibited significantly lower FVIII, FXIII, plasminogen, higher VWF levels, decreased peak thrombin and enhanced clot lysis vs. controls." (PMID 40303405, 2025). "On the other hand, parameters demonstrating a decrease in case of moderate/severe COVID-19 (e.g. FVIII activity, plasminogen activity, FXIII and FXIII-B levels) showed a positive correlation with the days elapsed since the positive SARS-CoV-2 test result." (PMID 40303405, 2025). "Although the occurrence of PPH was similar between COVID-19+ and control groups, in COVID-19+ women with PPH, prolonged APTT and lower plasminogen levels were observed." (PMID 40303405, 2025). "Insoluble microclot compositions from COVID-19 patients have been further shown to comprise Coagulation Factor XIII, plasminogen, fibrinogen alpha-chain, a2-antiplasmin, von Willebrand Factor, C-reactive protein, SAA-4 and complement component C7." (PMID 36998202, 2023). "The results showed that significant targets of Vitex negundo compounds in COVID-19 are CSB, SERPINE1, and PLG which code for cathepsin B, plasminogen activator inhibitor-1, and plasminogen, respectively." (PMID 37037462, 2023). "To assess the changes in the fibrinolytic system, we measured α2AP, plasminogen, TAFI, tPA, PAI-1, D-dimer, and fibrinogen levels in all the COVID-19 patients." (PMID 37629265, 2023). "We assessed the levels of fibrinolytic markers, such as α2AP, plasminogen, PAI-1, tPA, and TAFI, in COVID-19 patients." (PMID 37629265, 2023).